HESX1 (HESX homeobox 1)
Description:
Required for the normal development of the forebrain, eyes and other anterior structures such as the olfactory placodes and pituitary gland. Possible transcriptional repressor. Binds to the palindromic PIII sequence, 5'-AGCTTGAGTCTAATTGAATTAACTGTAC-3'. HESX1 and PROP1 bind as heterodimers on this palindromic site, and, in vitro, HESX1 can antagonize PROP1 activation.
Synonyms: RPX; ANF; CPHD5
Tractability: No criterion of Open Targets' tractability assessment is met for any kind of drug.
Gene: Protein-coding gene on chromosome 3 (57,197,838 to 57,227,606, reverse strand). Ensembl gene ENSG00000163666.
Subcellular location: Nucleus
Subcellular location (Human Protein Atlas): Nucleoplasm
Gene Ontology:
Molecular function: DNA binding; DNA-binding transcription repressor activity, RNA polymerase II-specific; protein binding; RNA polymerase II cis-regulatory region sequence-specific DNA binding; RNA polymerase II transcription regulatory region sequence-specific DNA binding; sequence-specific double-stranded DNA binding; DNA-binding transcription factor activity, RNA polymerase II-specific; chromatin binding; protein homodimerization activity; sequence-specific DNA binding
Biological process: gene expression; negative regulation of transcription by RNA polymerase II; pituitary gland development; brain development; regulation of transcription by RNA polymerase II; forebrain development; regulation of DNA-templated transcription
Cellular component: nucleus; chromatin; protein-DNA complex
Genetic constraint (gnomAD): Loss-of-function variants: 8 observed, 17.19 expected, observed/expected ratio (o/e) 0.47, 90% interval 0.27 to 0.84. The upper end of that interval is the gene's LOEUF score, 0.84, which puts it in group 3 of 6, group 1 being the genes least tolerant of losing a copy. Missense variants: 168 observed, 178.16 expected, observed/expected ratio (o/e) 0.94, 90% interval 0.83 to 1.07. Synonymous variants: 57 observed, 64.17 expected, observed/expected ratio (o/e) 0.89, 90% interval 0.72 to 1.11.
Homologues: Orthologues: chimpanzee HESX1 (98% identical), macaque HESX1 (95% identical), dog HESX1 (89% identical), pig HESX1 (86% identical), rabbit HESX1 (86% identical), guinea pig HESX1 (83% identical), rat Hesx1 (82% identical), mouse Hesx1 (81% identical), tropical clawed frog hesx1 (58% identical). Paralogues in human: PAX7 (29% identical), RAX (29% identical), PHOX2B (28% identical), VSX2 (28% identical), PAX3 (28% identical), GSC (26% identical), PAX6 (26% identical), ARX (26% identical), PRRX2 (25% identical), ALX3 (25% identical), PHOX2A (25% identical), ESX1 (24% identical), and 38 more.
Diseases named in the same sentence as HESX1 in open-access papers:
HESX1 is named in the same sentence as 32 diseases in open-access papers, as found by Europe PMC text mining. Sharing a sentence is not in itself a finding about the gene and the disease. The quoted sentences say what the papers report.
hypopituitarism (15 papers, 2006 to 2025). A condition of diminution or cessation of secretion of one or more hormones from the anterior pituitary gland. "Sibling patients 38 and 39 with hypopituitarism harbored a likely benign variant in the HESX1 gene, which was inherited from the unaffected mother." (PMID 37940764, 2024). "The HESX1 variant was described as causative in a few subjects with an incompletely penetrant dominant form of combined pituitary hormone deficiency (CPHD)." (PMID 33451138, 2021). "Mutation frequencies of PROP1, POU1F1 and HESX1 in patients with combined pituitary hormone deficiencies (CPHD) vary substantially between populations." (PMID 29255988, 2018). "Mutations in several genes are known to cause hypopituitarism in children, and the pituitary transcription factors HESX1, PROP1 and POU1F1 (PIT1) are among them." (PMID 27351100, 2016). "The pituitary transcription factors LIM Homeobox 3(LHX3), SRY-Box 2 (SOX2) and HESX homeobox 1 (HESX1) are vital for early patterning of the forebrain and pituitary, and mutations in these developmental genes result in syndromic hypopituitarism with gonadotropin deficiency in humans." (PMID 29730183, 2018). "Six3 can interact genetically with Hesx1, causing activation of WNT signaling and hypopituitarism associated with pituitary gland dysmorphology." (PMID 35951005, 2023). "The pituitary transcription factors HESX1, LHX3, and SOX2 are vital for early patterning of the forebrain and pituitary, and mutations in these developmental genes result in syndromic hypopituitarism with gonadotropin deficiency in humans." (PMID 31220230, 2019). "Mutations in several transcription factors, including HESX1, PROP1 and POU1F1 cause pituitary hormone deficiency in mice and humans." (PMID 27351100, 2016). "Patients with mutations in transcription factors (eg PROP1, HESX1, SOX3) require long-term surveillance for evolving ACTH and other pituitary hormone deficiencies." (PMID 26416826, 2015). "The HESX1 gene has been identified as a cause of SOD and hypopituitarism, and we also identify a Hesx1 model on rank 22 using our approach." (PMID 22719993, 2012). "Therefore, mutations of HESX1 are associated with isolated GH deficiency (IGHD) and combined pituitary hormone deficiency (CPHD)." (PMID 34948037, 2021). "HESX1, GLI2, and SOX3 mutations have been linked to hypopituitarism, and mutations in SOX2, LHX3, LHX4, and PROP1 may cause gonadotropin deficiency." (PMID 34948037, 2021). "Indeed, it has been shown that mutations in human HESX1 are associated with familial cases of SOD and other forms of hypopituitarism [combined pituitary hormone deficiency (CPHD) and isolated growth hormone deficiency (IGHD)]." (PMID 17931718, 2008). "In conclusion, extra-pituitary findings may provide clues for the diagnosis of particular gene mutations including GLI2, HESX1, LHX4, SOX3, and OTX2 which are involved in the development and differentiation of the pituitary gland resulting in a variety of pituitary hormone deficiencies." (PMID 31782289, 2020). "There are many causative genes for its isolated form or for multihormonal hypopituitarism, such as TSHβ, TRHR, TBL1X and IRS4 (for heritable isolated central hypothyroidism) and PROP1, HESX1, SOX3 (for multihormonal hypopituitarism)." (PMID 39997750, 2025). "Future studies will reveal whether the identified HESX1 partners may be involved in the aetiology and pathogenesis of human syndromes, such as SOD and hypopituitarism." (PMID 17931718, 2008).
Septo-optic dysplasia (8 papers, 2014 to 2025). Septooptic dysplasia (SOD) is a clinically heterogeneous disorder characterized by the classical triad of optic nerve hypoplasia, pituitary hormone abnormalities and midline brain defects. "In septo-optic dysplasia there are few family cases, the majority of cases being sporadic; thus, less than 1% of septo-optic dysplasia patients have mutations in the genes Hesx1, Sox2, Sox3, or Otx2." (PMID 33324176, 2020). "Mutations in the homeobox gene HESX1 are commonly associated with PSIS, which is characterized by septo-optic dysplasia, isolated GHD or multiple hormone deficiencies (including central diabetes insipidus), and delayed puberty." (PMID 40539145, 2025).
Anophthalmia (3 papers, 2014 to 2019). Absence of the globe or eyeball. "HESX1 is essential for correct development of the forebrain, and Hesx1 null mice display postnatal lethality probably caused by CNS defects comprising anophthalmia, a reduced prosencephalon and pituitary dysplasia." (PMID 25587054, 2015).
congenital hypopituitarism (2 papers, 2008 to 2010). "Moreover, the possibility exists for a more direct contribution of HESX1-interacting proteins in human disease, i.e., mutations in HESX1 partners might also lead to congenital hypopituitarism and SOD." (PMID 17931718, 2008).
absence seizures (1 paper, 2025). "Four genes-HESX1, NCKAP1, SON, STARD9-had not been previously associated with absence seizures." (PMID 41137852, 2025).
adenoma (1 paper, 2021). A neoplasm arising from the epithelium. "In all three published mouse models, such as the global Aip heterozygous or the conditional Gh-specific or Hesx1-specific Aip-knockouts, pituitary hyperplasia is present many weeks before the appearance of adenomas." (PMID 34588620, 2021).
atherosclerosis (1 paper, 2025). A disease characterized by the build-up of fatty material and calcium deposition in the arterial wall resulting in partial or complete occlusion of the arterial lumen. "After intersection analysis, three regulons (DLX2, HESX1, and KDM2A) were identified as master TRs in atherosclerosis." (PMID 40303308, 2025).
brain injuries (1 paper, 2021). "In turn, mutations of other transcription factors (e.g., PIT-1/POU1F1, PROP-1, LHX3, SOX2, SOX3, OTX2 and HESX1) lead to congenital MPHD, while hypothalamic-pituitary tumours (e.g., craniopharyngiomas), their treatment regimens or traumatic brain injuries result in acquired MPHD." (PMID 34445772, 2021).
epilepsy (1 paper, 2020). A brain disorder characterized by episodes of abnormally increased neuronal discharge resulting in transient episodes of sensory or motor neurological dysfunction, or psychic dysfunction. "Other genes with polymorphisms validated in the GASH/Sal, namely Tsen54, Hesx1 and SLC12a1, are also related to epilepsy, albeit secondarily because polymorphisms in these genes are primarily associated with other diseases." (PMID 32168507, 2020).
Granuloma (1 paper, 2014). A compact, organized collection of mature mononuclear phagocytes, which may be but is not necessarily accompanied by accessory features such as necrosis. "In addition, the expression of HESX1 and TNFSF10 genes was greater in C. burnetii-induced granulomas than in BCG-induced granulomas." (PMID 25566510, 2014).
osteoporosis (1 paper, 2021). A condition of reduced bone mass, with decreased cortical thickness and a decrease in the number and size of the trabeculae of cancellous bone (but normal chemical composition), resulting in increased fracture incidence. "Present results further elucidate the inheritance pattern of HESX1 variants and recommend assessing the clinical impact of variants located in C-terminal propeptide of COL1A1 gene for their potential association with rare recessive and early onset forms of osteoporosis." (PMID 33451138, 2021).
panhypopituitarism (1 paper, 2020). Insufficient production of all the anterior pituitary hormones. "Hesx1 exon sequencing has revealed different mutations in patients with panhypopituitarism who present with hypoglycemic seizures." (PMID 32168507, 2020).
psoriasis (1 paper, 2021). An autoimmune condition characterized by red, well-delineated plaques with silvery scales that are usually on the extensor surfaces and scalp. "In spite that these results must be validated in vitro and in vivo with a functional genomics approach, we propose FOXP2, RUNX2, NR2F1, ELF1 and HESX1 transcription factors (those with the highest FIF on each gene) as novel drug targets for psoriasis." (PMID 33898962, 2021).
Salmonella Infections (1 paper, 2023). Infections with bacteria of the genus SALMONELLA. "Among the multiple genes detected in this study, EXFABP, S100A9/12, CEMIP, FKBP5, MAVS, FAM168B, HESX1, EMC6, and others were found as potential candidate gene and transcript (co-) factors for resistance to Salmonella infection." (PMID 36902251, 2023).
schizencephaly (1 paper, 2010). "Given the evidence for a role of HESX1 in SOD and the frequent association between SOD and schizencephaly, we hypothesized that HESX1 mutations might be responsible for some proportion of simplex cases of schizencephaly." (PMID 20949537, 2010). "In three patients with schizencephaly, including one with SOD features (Patient 3) we observed an apparent heterozygous missense mutation in HESX1, c.374A > G (p.Asn125Ser)." (PMID 20949537, 2010). "Because of the overlap sometimes observed between schizencephaly and SOD, we also hypothesized that genes associated with SOD—HESX1 and SOX2—might also cause some cases of schizencephaly." (PMID 20949537, 2010). "Analysis of sequencing of the LHX2, HESX1, and SOX2 exons and exon–intron junctions in 97 cases of schizencephaly did not reveal mutations that were likely to be pathogenic." (PMID 20949537, 2010).
T-cell immunodeficiency (1 paper, 2017). A broad classification of disorders that affect the cell-mediated aspect of the immune response. "Genes central in both mouse networks, include FOXN1 and HESX1, related to T-cell immunodeficiency and septo-optic dysplasia respectively." (PMID 29161290, 2017).
viral infections (1 paper, 2022). "The 8-gene signature included three genes over-expressed in bacterial infections (SMARCD3, ICAM1, EBI3; “bacterial genes”) and five over-expressed in viral infections (JUP, SUCLG2, IFI27, FCER1A, HESX1; “viral genes”)." (PMID 36543117, 2022).
tumour (4 papers, 2017 to 2021). "These lesions showed a similar marker profile to Hesx1-Cre-targeted tumours, with positive p63 and AE1/AE3 staining." (PMID 30912742, 2019). "We show that expression of oncogenic β-catenin in Hesx1+ embryonic precursors also results in stem cell clusters and paracrine tumours." (PMID 29180744, 2017). "Together, these findings demonstrate that the activation of oncogenic β-catenin in Hesx1+ pituitary embryonic precursors leads to cell transformation and formation of somatic mutations-bearing tumours, which are mostly not derived from the Hesx1 cell lineage." (PMID 29180744, 2017). "An interesting finding from the analysis of the embryonic model is that if oncogenic β-catenin is expressed in committed or differentiated pituitary embryonic cell types, rather than in Hesx1-expressing undifferentiated precursors, clusters do not form and tumours never develop." (PMID 34019103, 2021). "In this paper, we show that the expression of oncogenic β-catenin and activation of the WNT pathway in Hesx1+ embryonic pituitary precursors or Sox2+ pituitary stem cells in young mice results in the activation of a robust SASP in targeted cells and the subsequent paracrine formation of tumours." (PMID 29180744, 2017). "However, the deletion of Apc in both Hesx1-expressing embryonic precursors, or SOX2 + adult stem cells, completely fails to generate ACP-like tumours." (PMID 34019103, 2021). "Therefore, the expression oncogenic β-catenin in either SOX2 + adult stem cells or HESX1 + embryonic progenitors leads first to the formation of clusters, which are similar to those found in human ACP, and then promote tumour formation in a cell non-autonomous manner." (PMID 34019103, 2021).
infection (1 paper, 2023). The state of being infected such as from the introduction of a foreign agent such as serum, vaccine, antigenic substance or organism. "The FAM168B, RAF1, HESX1, USP8, C2CD5, PIGC, ENSGALG00000053041, and ENSGALT00000092369 were found to be top driver genes shared among dpi, body weight post-infection, and propionate and valerate cecal contents." (PMID 36902251, 2023).
HESX1 also shares sentences with these, for which no sentence is quoted: Gonadotropin deficiency (2 papers); holoprosencephaly (2); microphthalmia (2); bacterial infections (1); Central diabetes insipidus (1); coloboma (1); craniopharyngioma (1); Esophageal atresia (1); genetic disorder (1); optic nerve hypoplasia (1); pituitary stalk interruption syndrome (1); polydactyly (1); tuberculosis (1).